CD4 (CD4 molecule)
Diseases named in the same sentence as CD4 in open-access papers (continued):
Sharing a sentence is not in itself a finding about the gene and the disease.
tumor (continued). "The frequency of CD4+ lymphocytes with a memory phenotype is reported to significantly increase in patients with tumor free lymph node, and the generation of memory response against tumor antigens and may prevent tumor relapse in patients with different cancers, which predict a longer survival." (PMID 32012118, 2020). "Such beneficial effects of prevaccination are in part explained by the potentiation of CD4 and CD8 T‐cell infiltration in the treated tumor." (PMID 31746149, 2020). "In our study, PCC0208025 not only decreased the percentage of Treg (CD4+CD25+CD127low/− T cells), but also increased the ratios of CD8+/Treg in tumor." (PMID 32214351, 2020). "In our analysis, blood DP T cells were mostly TEMRA cells, but similar to CD4+ and CD8+ TILs, DP T cells in the tumour comprised primarily of TEM cells." (PMID 32439888, 2020). "In the MC38 model, both single-agent treatments induced proliferation of CD4+ and CD8+ tumor-infiltrating lymphocytes, and to a higher degree in combination." (PMID 33425754, 2020). "Fluorescent multiplex IHC (mIHC) for simultaneous staining CD4, CD8, PD1, TIM3 and cytokeratins were conducted in paired pre‐NAT and post‐NAT tumor samples." (PMID 32894006, 2020). "To explore the chemokines and chemokine receptors involved in T cell trafficking from blood to the tumour in this macaque model, we quantified the mRNA levels of all known chemokine receptors in CD4+ and CD8+ T cells sorted from the tumour tissue and PB." (PMID 32439888, 2020). "Neutralization of CD4, CD8, CXCL9, and CXCL10 abrogated the anti-tumor activity of combined therapy." (PMID 33167311, 2020). "The efficacy was attributed to the local activation of T-lymphocytes with significant activation of CD4+ and CD8+ T-cells leading to tumor necrosis." (PMID 33066447, 2020). "Up-regulation of stress-induced ligands, including ULBP2, allows tumor cell recognition by immune cells trough the NKG2D receptor expressed on lymphocytes, Natural Killer cells, as well as cytotoxic, CD4 or γδ T cells." (PMID 32604720, 2020). "Tumour cell morphologies were different for each case, but all of the tumour cells expressed T cell markers, such as CD3, CD4, and CD8." (PMID 32238190, 2020). "The mRNASig were closely related to a variety of tumor-infiltrating lymphocytes, especially including CD8+ T cells, activated CD4+ memory T cells, regulatory T cells, activated NK cells, and resting NK cells." (PMID 33101364, 2020). "Type II Interferon (IFN)-γ acts on tumor cells, enhancing their recognition by CD8+ T cells as well as by CD4+ T cells, and unveiling a key role in the promotion of tumor immunogenicity." (PMID 32000794, 2020). "Analysis of the tumor CD3+ T cell populations revealed that proinflammatory CD8+IFN-γ+ T cells were significantly increased in RaptorECKO tumors, and CD4+IFN-γ+ T helper cells were moderately increased." (PMID 32759497, 2020). "Depletion of either CD4+ or CD8+ T cells before vaccination and throughout the tumor study allowed us to dissect which T cell subset is responsible for the observed effect of the peptide and SLP–Lpx vaccines." (PMID 33298945, 2020). "As MDV is an intracellular pathogen that infects and transforms CD4+ T cells, the host cell-mediated immune response is considered to be vital for controlling MDV replication and tumor formation." (PMID 32987648, 2020). "These cells can control tumor growth through either directly killing tumor cells, as NK and CD8+ T cells, or indirectly, in the case of CD4+ T cells, which secrete cytokines capable of activating other effector leukocytes." (PMID 33335860, 2020). "Similar observations were made previously in the tumor microenvironment, where lactate is imported into CD4+ T cells by SLC5A12, decreasing CD4+ T cell motility while inducing IL-17 production." (PMID 33086598, 2020).
tumor (continued). "Other in vivo studies reported recovery or increase in the levels of circulating or tumor-infiltrating CD4+ and CD8+ T cells and of NK cells, and a decreased number of tumor-infiltrating MDSCs after administration of CUR or a CUR-based cocktail." (PMID 32423101, 2020). "The matured DCs form CD4+ and CD8+ (helper and killer) T-cells with appropriate tumor-specific information, preparing them for tumor-specific immune attack." (PMID 33014841, 2020). "CD4+ and CD8+ T cells are subtly synchronized with each other within PDAC tumours; only patients with both CD4- and CD8-positive T cells have a significantly increased OS rate, and the CD4/CD8 double-positive T cell status is an independent prognostic factor." (PMID 32061257, 2020). "P2 subgroup had significantly higher number of tumor-infiltrating CD8+ T cells, CD4+ T cells, helper T cells, activated natural killer cells and lower number of M2 macrophage than P1, suggesting an enhanced immunosurveillance in P2 subgroup." (PMID 33378744, 2020). "We observed that on average, CD3 + CD4-CD8- T-cells, CD4+ helper T-cells, and CD8+ cytotoxic T-cells were about 11 um further from tumor cells than myeloid cells were, whereas B-cells were 13 um further away than T-cells were." (PMID 32723384, 2020). "IO@FuDex3's ability to reverse immunosuppressive tumor microenvironment (TME) was noted where CD3+CD8+and CD3+CD4+ T‐cell population was significantly enhanced, and Treg was reduced." (PMID 32328428, 2020). "Mice irradiated with FLASH PT presented smaller tumours with an increased recruitment of CD4+ and CD8+ T cells in the tumour core than standard dose-rate irradiation." (PMID 32635552, 2020). "This treatment enhanced the presence of tumor-reactive CD8+ and CD4+ T cells in primary tumors and tumor-draining lymph nodes." (PMID 32178288, 2020). "CD4 and CD8 T cells from the spleens of mice were purified with Miltenyi beads following vaccination with DC tumor lysate vaccine." (PMID 32570793, 2020). "In a follow-up experiment, we observed increased CD4+ and CD8+ T cells in the TUBO tumour of WT BALB/c mice treated with anti-neu mAb." (PMID 32127568, 2020). "As for vector-dependent immunogenicity, it has been demonstrated that lentivirus-based vectors elicit a strong tumor-specific CD8+ and CD4+ T cell response." (PMID 32150821, 2020). "In the inflamed type there are CD4+ and CD8+ T cells within the tumor stroma and between tumor cells." (PMID 35582213, 2020). "Our meta-analysis confirmed that high densities of TILs, CD3+TILs, CD4+TILs, CD8+TILs and CD20+TILs in the tumour nest are favourable prognostic biomarkers for patients with NSCLC, and Foxp3+TILs in the tumour stroma are a poor prognostic biomarker." (PMID 33170901, 2020). "The same correlation was observed in the blood of tumor patients (CD8+ Tc cells: p < 0.05, R2 = 0.03; CD4+ Th cells: p < 0.1, R2 = 0.04; Treg: p < 0.05, R2 = 0.07)." (PMID 32082401, 2020). "In general, the tendency for better clinical outcomes of patients with a high CD8/CD4 ratio is notable in HPSCC, despite the prognostic significance being very different from that in other tumours." (PMID 32758195, 2020). "The presence of T lymphocytes within the tumor microenvironment, especially the cytotoxic CD8+ subsets and to some extent the CD4+ subsets, have been shown to correlate with better prognosis of the patient." (PMID 32911646, 2020). "Th1 CD4+cells engage in canonical activation and recruitment of innate immune cells and CD8+ cells to direct anti-tumor immunity." (PMID 33362774, 2020). "This study suggests that CD4+CD25+CD127lowTregs, TGF-β1, IL-10 are closely related to the occurrence and development of tumor." (PMID 32218692, 2020). "Compared to those in the PBMCs, the ratios of immune checkpoint-positive exhausted CD4+ T cells and CD8+ T cells were higher at the AG tumor sites." (PMID 33614475, 2020).
tumor (continued). "Immunophenotyping of the tumor-infiltrating lymphocyte populations revealed a decrease in the levels of CD4+CD25+ T cells and CD4+ effector memory cells and an increase in the population of central memory CD8+ T cells." (PMID 32843492, 2020). "In multicolour immunofluorescence LAG3 positive cells within the tumour microenvironment were seen with co-expression of CD3, CD4 and CD8." (PMID 32592066, 2020). "The results revealed that the ratio of tumor infiltrated CD8+ T cells was increased and the proportion of CD4+ Treg was reduced in the flank tumor." (PMID 32992835, 2020). "This M1 activation, characterized by elevated p38/p65 signaling and increased proinflammatory cytokines, promoted the infiltration and activation of CD4+ and CD8+ T cells in the tumor microenvironment." (PMID 32296017, 2020). "Immune cells as CD4+/CD8+ T cells, dendritic cells (DCs), and NK cells generate or mediate immune responses to eradicate potential tumor cells." (PMID 32595757, 2020). "Antigen-specific TSM cells have been well characterized in viral, parasitic and tumour-specific CD8+ T cells, and a recent report described M. tb-specific CD4+ TSM cells as the source of TCM and TEM cells." (PMID 32437421, 2020). "With respect to the immune profile of the mUM, we confirm our previous results that the main “reactive inflammatory” cell within these metastatic tumours is the M2 macrophage with an expression of CD68, CD163, and CD4." (PMID 33008022, 2020). "LLC tumor–bearing mice were treated with multiple doses of anti-CD4 or anti-CD8 neutralizing antibodies, the combination of anti-CD4/anti-CD8 antibodies, or with isotype-matched control IgGs." (PMID 32759497, 2020). "These modified T cells can perform the role of APCs and stimulate antigen-specific CD4+ T-dependent CD8+ T cell proliferation, expansion and anti-tumor effector responses in vivo." (PMID 32765528, 2020). "While we did not observe significant change in the infiltration pattern of TILs from LLC-1 tumor, we identified significant increase in both CD8 and CD4 T-cells in the combined treatment tumors, and CD8 in tumors treated with anti-PD-1 alone." (PMID 32144446, 2020). "Indeed, the livers of these CD200R1-deficient mice exhibited increased metastatic CD200+ tumor growth which contained higher numbers of CD11b+Ly6C+ myeloid cells, displayed VEGF and HIF1a gene expression with increased angiogenesis, and showed significantly reduced CD4+ and CD8+ T cell infiltration." (PMID 32635224, 2020). "Depletion of T regulatory (Treg) cells was shown to enhance their migration and ability to prime proinflammatory CD4+ T cells for IFN-γ production and tumor rejection." (PMID 32486257, 2020). "In the early stage of tumour formation, TIM-3+CD4+ T cells can secrete IFN-γ to have antitumor effects." (PMID 32461587, 2020). "Two patients in the 500-mg BID group exhibited an increase in CD4+ and CD8+ cells within CD45+ populations measured in fresh biopsy tumor samples." (PMID 31297636, 2020). "Moreover, CD4+T cell therapy could replace chemotherapy depending upon tumor size." (PMID 32148558, 2020). "At the end of study (> day 28 post-initiation of bintrafusp alfa treatment), there was a trend in the increase in CD4+ and a significant increase in CD8+ T-cell infiltration per milligram tumor when comparing bintrafusp alfa to control treated animals." (PMID 32373533, 2020). "Blockade of PD-L1 in γδ T cells enhanced CD4+ and CD8+ T-cell infiltration and induced tumor protection in murine PDAC." (PMID 32865617, 2020). "Significant increase in the frequency of IFN-γ+ CD8+ (~20%) and CD4+ (~10%) T cells was found in tumors from the hetIL-15-treated group, suggesting that hetIL-15 increases the production of IFN-γ within the tumor." (PMID 32461349, 2020). "In the recent report, FoxP3 expression in tumor-infiltrating CD4+ T cells is observed to overlap with the CD69 expression, suggesting that tumor-infiltrating Treg cells are a tissue-resident population." (PMID 33379384, 2020).
tumor (continued). "After exploring the role of G-CSF/G-CSFR in vitro in CD4+ T cell phenotypes, next, the impact of G-CSF/G-CSFR in CD4+ T cells in the tumor microenvironment on tumor growth was explored." (PMID 33042110, 2020). "We analyzed infiltration in the tumor body (TB) and invasive front (IF) and found that TB were infiltrated with CD3+, CD4+, and CD8+ cells––but mostly accumulated in the IF––while ROCKi did not alter distribution." (PMID 31935375, 2020). "DFMO treatment led to the recruitment of activated (IFNγ+) CD4+ T cells, CD8+ T cells and NK cells and an increase in tumour‐killing M1 macrophages in the tumour microenvironment of an ovarian cancer mouse model." (PMID 33030764, 2020). "There was a marked depletion in both CD4 + and CD8 + cell density at the invasive tumour-stroma margin and a reduction in the TLS area, an effect which was prolonged." (PMID 31901949, 2020). "In the tumor microenvironment, the number of CD4-expressing iNKT cells is increased in HCC tumors, thus producing more Th2 cytokines, preventing the expansion of tumor Ag-specific CD8+ T cells, and promoting tumor growth." (PMID 32770081, 2020). "We first showed conclusively that CD1d+ tumor/Gal in hematological malignancy models, including a lymphoma (EL4), leukemia (WEHI3B), and plasmacytoma (J558) model, can induce antigen-specific CD4+ and CD8+ T cell immunity." (PMID 32231116, 2020). "These primary xenografts consisted of human Tfh PD1+ CD4+ cells and cells from the TME (B cells, CD8 T cells, plasmocytes secreting IgGs), very similar to the engrafted original human AITL tumor." (PMID 32796826, 2020). "The activated DC migrates to the tumor draining lymph nodes and presents tumor-specific antigens to naive CD8 + or CD4 + T cells by MHC class I or MHC class II molecules, respectively (“first” signal)." (PMID 32695747, 2020). "Through several interactions including TRAIL, NKp46 and yet to be defined receptors, NK cells can lyse CD4+ and CD8+ T cells resulting in less effective adaptive responses thereby promoting pathogen and tumor persistence." (PMID 32733814, 2020). "In cancer patients a tumor response involving CD8+ T cells, TH1 CD4+ T cells, and IFNγ producing natural killer cells is associated with a better prognosis." (PMID 33344239, 2020). "MDSCs produce ROS-associated free radicals and immunoregulatory cytokines to inhibit host CD4+ and CD8+ T cell responses, thereby promoting tumor progression and metastasis." (PMID 32005273, 2020). "With the help of CD4+ T cells, CD8+ T cells successfully differentiate into CTL and exert its anti‐tumor effects." (PMID 32931665, 2020). "Regarding CD4+ TSCM, we observed that they were more frequent in tumor-involved lymph nodes and in patients with advanced-stage disease." (PMID 32228503, 2020). "Actually, the anti-PD-L1 treatment led to an increase in activated cytotoxic CD4+ T and CD8+ T cells in the TILs (IFNγ+CD4+ T cells and IFNγ+ CD8+ T cells) and resulted in an increased number of TUNEL-positive cells in 4T1-WT tumours." (PMID 32732922, 2020). "To characterize the functional properties of TILs in this macaque tumour model, we sorted CD4+ and CD8+ T cells from the tumour tissue as well as from PB and quantified the mRNA levels of cytokines in these populations." (PMID 32439888, 2020). "Although CD4+CD8+ double-positive T cells are critical for T-cell development in the thymus, these T cells are functionally immature and have insufficient anti-tumor activity against TETs12." (PMID 32132638, 2020). "Reactivating the resting CD4 memory T cells existing in the lung tumor microenvironment can induce brisker proliferative capacity and secretion of IFN-γ to eliminate tumor cells." (PMID 33102584, 2020). "FACS analysis showed that knockdown of Fbp1 significantly decreased tumor infiltration of CD45+CD8+ T and CD45+CD4+ T cells, but increased the infiltration of CD11b+Gr1+ myeloid-derived suppressor cells (MDSCs)." (PMID 31938049, 2020).
tumor (continued). "Combination treatment achieved better tumor control than monotherapy, and the activities of CD8+ and CD4+ T cells were further enhanced when compared with monotherapy." (PMID 32929370, 2020). "It is generally believed that B cells can be used as antigen-presenting cells to induce CD4+ T cell–dependent CD8+ memory T cells, thereby helping to control tumor invasion and metastasis." (PMID 32852285, 2020). "In PBMCs, the proportions of PD-1+CD4+ cells were higher than those of PD-1+CD8+ cells, but the proportions of the two in tumours were comparable." (PMID 32616847, 2020). "For newly diagnosed GBM, autologous vaccination with tumor lysate-pulsed DC enhanced the precursor frequency of CD4+ T and CD4+ interferon (IFN) γ-producing cells, suggesting an induced tumor-specific CTL response." (PMID 33228738, 2020). "The role of CD4 + T-cells is crucial for expansion and accumulation of other antigen-specific immune cells, and the participation of CD8 + cells in tumor killing activity has been confirmed by many studies." (PMID 33199774, 2020). "CD4 and CD8 T cells have been previously shown to play critical role in BCG-mediated anti tumor activity, mostly in animal models or inferred from markers related to T cell activities." (PMID 33584702, 2020). "DCs combined with antigens from a tumor or virus can produce major histocompatibility complex (MHC) class I and class II peptide epitopes to CD8 and CD4 T lymphocytes, leading to a series of immune reactions in response to the antigens." (PMID 33363088, 2020). "We detected CD3+, CD4+, and CD8+ lymphocytes from single-cell suspensions of tumor tissues by flow cytometry." (PMID 33260160, 2020). "Measures of TIL quality including the proportion of tumor-reactive CD8+ and CD4+ TILs, and TIL response polyfunctionality were determined." (PMID 33198174, 2020). "CD4+ and CD8+ T cells isolated from tumours of Fgf2LMW−/− mice had increased RNA expression of Il6, Il12, and Il17 compared with T cells isolated from WT mice." (PMID 32792542, 2020). "We compared the methylation status of the NT5E gene according to the expression of inflammatory markers including TNF-α, IL-4, NF-κB p50, CD4+, and CD8+ T cells, CD68+ macrophages, intratumoral and peritumoral inflammation in tumor tissues." (PMID 33198064, 2020). "Based on the Cibersort algorithm, the abundances of infiltrating immune cells (CD4+ T cells, CD8+ T cells, B cells, neutrophils, dendritic cells, and lymphocytes) in the tumor samples were estimated." (PMID 32571262, 2020). "First, we transferred immune CD4+ or CD8+ T cells into naïve syngeneic recipients and assessed the capacity of these cells to protect the mice from parental tumor challenge." (PMID 33138029, 2020). "In the presence of APC, DC-derived exosomes have been reported to load multiple peptide antigens (e.g., MHC I, MHC II), and thereby stimulating both CD4+ helper T cells and CD8+ CLTs to participate in the anti-tumor response." (PMID 33183286, 2020). "Bacterial ablation in PDAC bearing mice reduced MDSC populations, increased M1 macrophage populations, promoted differentiation of CD4+ T cells, and activated CD8+ T cells to reduce tumor growth." (PMID 32509781, 2020). "Our study further provides insight into the spatial distribution of CD4+, CD8+, PD1+CD8+, PD1+CD4+, TIM3+CD8+, and TIM3+CD4+ cells within different areas of the tumor." (PMID 32894006, 2020). "CCL7 deficiency impairs the infiltration of cDC1 in the TME and the subsequent expansion of CD8+ and CD4+ T cells in bronchial draining lymph nodes and TME, thereby promoting tumor development in the KP mouse model." (PMID 33257678, 2020). "The proliferation of reactivated CD4+ cells and their production of IFN-γ facilitated tumor destruction." (PMID 33178203, 2020). "For instance, when CD4+FOXP3+ T cells were used as the RC, the MIN distance of tumor cells was 11.12 μm of P2433 and 28.83 μm of P7422; the MIN distance, of CD8+ T cells, was 19.60 μm of P2433 and 8.6 μm of P7422." (PMID 32377339, 2020).